TBPL1 (TATA-box binding protein like 1)
Description:
Part of a specialized transcription system that mediates the transcription of most ribosomal proteins through the 5'-TCT-3' motif which is a core promoter element at these genes. Seems to also mediate the transcription of NF1. Does not bind the TATA box.
Synonyms: STUD; TLF; TLP; TRF2; MGC:8389; MGC:9620
Tractability: PROTAC: ubiquitination databases record sites on it; its protein half-life has been measured.
Gene: Protein-coding gene on chromosome 6 (133,952,170 to 133,990,432, forward strand). Ensembl gene ENSG00000028839.
Subcellular location: Cytoplasm; Nucleus
Subcellular location (Human Protein Atlas): Nucleoplasm; Nucleoli
Gene Ontology:
Molecular function: protein binding; RNA polymerase II core promoter sequence-specific DNA binding; RNA polymerase II general transcription initiation factor activity; general transcription initiation factor activity; DNA binding
Biological process: transcription by RNA polymerase II; DNA-templated transcription initiation
Cellular component: nucleoplasm; cytoplasm; nucleus; transcription factor TFIIA complex
Genetic constraint (gnomAD): Loss-of-function variants: 3 observed, 18.41 expected, observed/expected ratio (o/e) 0.16, 90% interval 0.073 to 0.42. The upper end of that interval is the gene's LOEUF score, 0.42, which puts it in group 1 of 6, group 1 being the genes least tolerant of losing a copy. Missense variants: 110 observed, 211.07 expected, observed/expected ratio (o/e) 0.52, 90% interval 0.45 to 0.61. Synonymous variants: 58 observed, 66.89 expected, observed/expected ratio (o/e) 0.87, 90% interval 0.7 to 1.08.
Homologues: Orthologues: chimpanzee TBPL1 (100% identical), dog TBPL1 (100% identical), macaque TBPL1 (100% identical), mouse Tbpl1 (100% identical), guinea pig TBPL1 (92% identical), tropical clawed frog tbpl1 (92% identical), pig TBPL1 (92% identical), rat Tbpl1 (91% identical), zebrafish tbpl1 (78% identical), Drosophila melanogaster Trf2 (56% identical), Caenorhabditis elegans tlf-1 (39% identical). Paralogues in human: TBP (40% identical), TBPL2 (40% identical).
Diseases named in the same sentence as TBPL1 in open-access papers:
TBPL1 is named in the same sentence as 13 diseases in open-access papers, as found by Europe PMC text mining. Sharing a sentence is not in itself a finding about the gene and the disease. The quoted sentences say what the papers report.
breast carcinoma (2 papers, 2021 to 2023). "TATA box‐binding protein‐like protein 1 (TBPL1), the parental gene of circTBPL1, was reported to promote the progression of colorectal cancer, however, the specific function of TBPL1 in breast cancer is unclear." (PMID 37495592, 2023). "To elucidate how circTBPL1 regulated breast cancer progression, we firstly investigated whether circTBPL1 influenced the expression of its parental gene-TBPL1." (PMID 37495592, 2023).
pulmonary fibrosis (2 papers, 2020 to 2021). Chronic progressive interstitial lung disorder characterized by the replacement of the lung tissue by connective tissue, leading to progressive dyspnea, respiratory failure, or right heart failure. "Taken together, our results identify a surprising and potent role for the core circadian-clock factor REVERBα in the activation of myofibroblasts via a pathway incorporating a poorly characterized transcription factor, TBPL1, which affects the development of pulmonary fibrosis." (PMID 31879343, 2020). "In addition, TBPL1 was up-regulated in pulmonary fibrosis, correlating with REVERBα expression." (PMID 31879343, 2020).
astrocytoma (1 paper, 2020). "From the 10 strongest associations, only TBPL1, MYPOP and BMP7 appeared to be differently expressed in astrocytoma, albeit not specific to only astrocytoma." (PMID 33057419, 2020).
malignant glioma (1 paper, 2022). A grade III or grade IV glioma arising from the central nervous system. "Knockdown of hsa‐miR‐424 or overexpression of AC020907.1, Y_RNA, TMEM72‐AS1, KRT16P2, DLX6‐AS1, AP002414.1, and TBPL1 could regulate these three pathways to suppress malignant glioma tumorigenesis and progression." (PMID 35194922, 2022). "The eleven genes within the circadian rhythm pathway (AC020907.1, Y_RNA, TMEM72‐AS1, KRT16P2, DLX6‐AS1, AP002414.1, hsa‐miR‐424, TBPL1, NPAS2, CRY2, and ETNK1) were used to construct a model to evaluate the importance of these genes in malignant glioma." (PMID 35194922, 2022). "During the process of illustrating the circadian rhythm pathway, among the 6 coding genes, we exhibited the biological functions of TBPL1, NPAS2, CRY2, and ETNK1; therefore, what are the roles of VPS33B and C9ORF40 in malignant glioma?" (PMID 35194922, 2022). "Fourteen genes within the tumour immune microenvironment pathway (AC020907.1, Y_RNA, TMEM72‐AS1, KRT16P2, DLX6‐AS1, AP002414.1, hsa‐miR‐424, TBPL1, NPAS2, CRY2, VPS33B, CT62, DPY19L2P1, and KCNH1‐IT1) were used to construct a model to evaluate the importance of these genes in malignant glioma." (PMID 35194922, 2022). "Fourteen genes within the cellular senescence pathway (AC020907.1, Y_RNA, TMEM72‐AS1, KRT16P2, DLX6‐AS1, AP002414.1, hsa‐miR‐424, TBPL1, NPAS2, CRY2, C9ORF40, AL136115.1, AC102941.1, and AC008738.2) were used to construct a model to evaluate the importance of these genes in malignant glioma." (PMID 35194922, 2022). "Since all three pathways act through AC020907.1, Y_RNA, TMEM72‐AS1, KRT16P2, DLX6‐AS1, AP002414.1, hsa‐miR‐424, TBPL1, NPAS2, and CRY2, these genes could serve as potential therapeutic targets for malignant glioma." (PMID 35194922, 2022).
tumor (5 papers, 2015 to 2024). "miR-133b can function as a tumor suppressor and negatively regulate TATA box-binding protein-like protein 1 (TBPL1), a novel target of miR-133b in CRC that is associated with cell proliferation." (PMID 26307974, 2015). "In addition, five other genes, including TBPL1, USP28, NRG3, PPM1L, and RGR, were regulated by eRNAs expressed only in LGG tumor tissue; whereas SEMA4G was regulated by LGG-specific seRNAs." (PMID 35299740, 2022).
TBPL1 also shares sentences with these, for which no sentence is quoted: cancer (3 papers); colorectal cancer (2); gastric cancer (2); glioma (2); hepatocellular carcinoma (1); Herpes simplex infection (1); osteosarcoma (1); squamous cell carcinoma (1).